ALDH2 (aldehyde dehydrogenase 2 family member)
Diseases named in the same sentence as ALDH2 in open-access papers (continued):
Sharing a sentence is not in itself a finding about the gene and the disease.
cardiovascular diseases (58 papers, 2014 to 2026). "This study underscores the importance of personalized medicine and highlights the need for further research into the impact of ALDH2 polymorphisms on the treatment of cardiovascular diseases." (PMID 40979589, 2025). "Recent studies have shown that ALDH2 plays a crucial role in reducing the risk of cardiovascular disease by regulating cellular senescence." (PMID 38247467, 2023). "Aldehyde dehydrogenase 2 (ALDH2) is a mitochondrial enzyme that has been closely linked with an increased risk of cardiovascular diseases." (PMID 38247467, 2023). "ALDH2 polymorphism or mutation is associated with increased risk of cardiovascular disease, diabetic complications and neurodegenerative diseases, indicating it is a promising therapeutic target in treatment of many diseases." (PMID 37407961, 2023). "According to our previous studies, mitochondrial ALDH2 acts as endogenous protection in the heart, and it is closely associated with the development of several cardiovascular diseases." (PMID 36939783, 2021). "The ALDH2 rs671 genetic polymorphism has been linked with cardiovascular diseases (CVDs), but comprehensive epidemiological studies are lacking." (PMID 33276716, 2020). "Similarly, ALDH2 is involved in alcohol metabolism and has been associated with various health conditions, including cardiovascular diseases." (PMID 40303978, 2025). "However, the geographical distribution of ALDH2 polymorphisms in Chinese patients with cardiovascular diseases remains largely unexplored." (PMID 40979589, 2025). "Indeed, the ALDH2*2 variant with a single nucleotide polymorphism E487K that resides in the oligomerization domain is associated with cardiovascular disease, cancer, alcohol intolerance, and Alzheimer’s disease." (PMID 39796106, 2024). "Indeed, many (~40%) East Asians who carry a single nucleotide polymorphism (ALDH2 rs671) have an increased risk of cardiovascular disease (CVD)." (PMID 39796106, 2024). "ALDH2 has been implicated as a therapeutic target in cardiovascular diseases." (PMID 27736868, 2016). "However, studies suggest in humans the ALDH2*2 genetic variant limits excessive alcohol drinking, and the impact of ALDH2 genetic variants on cardiovascular disease may be mitigated." (PMID 39075523, 2024). "In another aspect, genetic susceptibility to higher levels of ALDH2, POLR2F, and ADPGK were associated with increased risks of various cardiovascular diseases." (PMID 40868097, 2025). "In recent years, it has become increasingly clear that the defective activation of ALDH2 is the main reason for the occurrence and development of various cardiovascular diseases." (PMID 40968356, 2025). "Here, we discuss the clinical implications and therapeutic potential of ALDH2-related autophagy and cell death in cardiovascular diseases." (PMID 40968356, 2025). "The importance of ALDH2 in cardiovascular diseases is also supported by studies in ALDH2 knockout (KO) mouse models, which display increased susceptibility to cardiac injury, enhanced oxidative stress, and reduced aldehyde clearance." (PMID 40723901, 2025). "Together, these studies suggest that the interplay between genetics and alcohol consumption is complex and requires future experimental and translational research to understand the interplay between alcohol, ALDH2 genetic, and cardiovascular disease." (PMID 39075523, 2024). "In particular, ALDH2 is believed to be involved in the ageing process and ageing related-cardiovascular diseases." (PMID 31947800, 2020). "Many studies have reported that ALDH2 plays a protective role in models of cardiovascular disease, whereas the lack or inhibition of ALDH2 exacerbates the consequences of MAO-A or MAO-B activation because of the accumulation of toxic aldehydes." (PMID 28044091, 2016). "Recent studies have demonstrated the protective effect of mitochondrial aldehyde dehydrogenase 2 (ALDH2) in cardiovascular diseases." (PMID 25313998, 2014).
cardiovascular diseases (continued). "Collectively, these data indicate that dysfunctional ALDH2 contributes to the pathogenesis of various cardiovascular diseases and could be a promising therapeutic target for their treatment." (PMID 40968356, 2025). "Targeting ALDH2 may simultaneously block oxidative damage and microcirculatory dysfunction, providing a novel therapeutic strategy for cardiovascular diseases and foundational evidence for optimizing post-MI ventricular remodeling treatments." (PMID 40642000, 2025). "The role of ALDH2 in cardiovascular disease is well-documented in the literature." (PMID 36782330, 2023). "Because Aldh2 oxidizes AA to acetic acid, it is well studied for its importance in alcohol metabolism and alcohol-induced stress complications, where it plays a critical role in alcoholic liver disease and cardiovascular disease." (PMID 35114580, 2022). "ALDH2 dysfunction initiates numerous diseases, such as cardiovascular diseases and cancer." (PMID 35169188, 2022). "In another study involving 500,000 men and women in China, the strong predictive value of ALDH2 genotypes on quantity of alcohol intake has been used to evaluate the effect of alcohol consumption on cardiovascular disease using the tool of Mendelian randomization." (PMID 35749303, 2022). "For patients with cardiovascular diseases, we should examine their ALDH2 genotype and living environment, whether they have consumed alcohol for a long time or live in high-elevation hypoxic conditions to achieve a more personalized and precise treatment plan." (PMID 36939783, 2021). "Given the important role for ALDH2 in cardiovascular diseases and the high prevalence of cardiac dysfunction in insulin resistance, this study was designed to evaluate the impact of ALDH2 in cardiac function in the sucrose diet feeding-induced insulin resistance." (PMID 27634872, 2016). "All these studies demonstrate that ALDH2 is very critical in cardiovascular diseases." (PMID 27736868, 2016). "Moderate alcohol intake might prevent cardiovascular diseases by activating ALDH2." (PMID 25313998, 2014). "The presence of ALDH2*2 significantly increased the risk of PSE in subjects without a history of alcohol consumption, suggesting that alcohol consumption may have an effect on the development of cardiovascular diseases." (PMID 25313998, 2014).
neurodegenerative disease (15 papers, 2013 to 2025). A disorder of the central nervous system characterized by gradual and progressive loss of neural tissue and neurologic function. "Previous studies have yielded diverse results when investigating the impact of ALDH2 polymorphisms on neurodegenerative diseases." (PMID 39290715, 2024). "ALDH2 gene polymorphism is a potential risk marker for an array of cardiovascular anomalies and neurodegenerative diseases." (PMID 36694633, 2023). "On the other hand, the case–control studies indicate that the deficiency of ALDH2 activity affects the risk of cardiovascular and neurodegenerative diseases." (PMID 34940794, 2022). "Therefore, decreased ALDH2 activity is involved in the pathogenesis of neurodegenerative diseases via various pathways associated with aldehydes accumulation and oxidative stress." (PMID 39290715, 2024). "Therefore, in future studies, for individuals with ALDH2 mutations, we can pay more attention to ShexCer and SM, to find out the relationship between the two types of sphingolipids and neurodegenerative diseases." (PMID 36743287, 2022). "Alcohol exposure with reduced ALDH2 activity and metabolism of toxic substances could be involved in the pathogenesis of neurodegenerative diseases." (PMID 39290715, 2024). "Due to its crucial role in maintenance of mitochondrial normal function, the use of ALDH2 activators would protect both vessels and neurons from neurotoxicity; thus, ALDH2 activation may represent a therapeutic target to treat neurodegenerative diseases." (PMID 32832006, 2020). "Seven genes were observed to be involved in both infections of three coronaviruses and two neurodegenerative diseases, including the HSP90AA1, ALDH2, CAV1, COMT, MTOR, IGF2R and HSPA1A." (PMID 37015947, 2023).
infection (11 papers, 2010 to 2025). The state of being infected such as from the introduction of a foreign agent such as serum, vaccine, antigenic substance or organism. "Cluster 1 which represents genes that are mostly reduced through the entire course of infection includes many metabolism related genes (e.g., Aldh2, Acad12, Acad10, P2rx7, Ldhb and others)." (PMID 39920132, 2025). "Retroviral RAD51 shRNA infection of Aldh2+/+ and Aldh2−/− MEFs led to efficient suppression of RAD51 expression, as assessed by immunoblotting." (PMID 28729482, 2017). "We achieved the stable knockdown of ALDH2 in Huh1 and Huh7 cells with lentivirus-mediated short hairpin RNA (shRNA) against ALDH2 using enhanced red fluorescent protein (ERP) as a marker for infection." (PMID 24454751, 2014). "ALDH2 was overexpressed in HCC cells using lentivirus infection." (PMID 39132147, 2024). "Infection of ALDH2-deficient VSMC with WT or C301S/C303S ALDH2 resulted in similar protein expression levels of 7.7 ± 1.2 and 5.9 ± 0.6 ng of ALDH2/μg of total protein for wild-type and mutated ALDH2, respectively." (PMID 27679490, 2016). "C. burnetii infections have been reported to induce a smaller oxidative burst in phagocytes, compared to several other infections, and the smaller change in the levels of Aldh2 in our samples may reflect this." (PMID 23990884, 2013). "A prediction that arises from our model is that oxidative stress, in response to infection by C. burnetii, could trigger an increase in lipoic acid production, with lipoic acid acting in an antioxidant capacity by recycling Aldh2 to its active, reduced state." (PMID 23990884, 2013).
heart diseases (10 papers, 2016 to 2023). "In 2009, Trends Cardiovascular Medicine predicted that ALDH2 would hopefully become a novel target for treatment of heart diseases." (PMID 32626739, 2020). "Previous research demonstrated that both HSF1 and ALDH2 are critical endogenous protective factors of the heart and play an important protective role in heart diseases." (PMID 32626739, 2020). "In addition, it has been reported that ALDH2 activation improved cardiac diseases by inhibiting autophagy, and ALDH2 was also reported to regulate the AKT-mTOR signaling cascade to maintain cardiomyocyte survival homeostasis." (PMID 37443810, 2023). "Previous studies have suggested that ALDH2 plays a central protective role in several types of cardiac diseases and global cellular oxidative stress mainly through metabolizing various aldehydes, such as 4-hydroxy-2-nonenal (4-HNE) which is the most abundant and reactive carbonyl species." (PMID 32292348, 2020).
metabolic disorders (8 papers, 2015 to 2025). "The collective findings from clinical and experimental studies underscore the role of ALDH2 deficiency as a critical genetic risk factor for cardiovascular and metabolic disease, particularly in East Asian populations." (PMID 40564981, 2025). "Our data highlight the therapeutic potential of reducing toxic aldehyde levels by activating ALDH2 for metabolic diseases." (PMID 37749090, 2023). "Here, the authors show an ALDH2 activator can treat these metabolic disorders in mice." (PMID 37749090, 2023).
liver (7 papers, 2018 to 2025). "For instance, ALDH2 is mainly associated with metabolic pathways in respiratory and digestive system tumors, metastasis-related pathways in THYM, and immune-related pathways in SKCM." (PMID 35096916, 2021). "Aldehyde dehydrogenase 2 (ALDH2) is a key enzyme for metabolism of reactive aldehydes, but its role during liver ischemia-reperfusion injury (IRI) remains unclear." (PMID 30671488, 2018). "A genetic predisposition in terms of ALDH-2 variants may amplify the susceptibility to carcinogenesis; indeed, East Asian populations, which have the highest prevalence of the ALDH-2 variant, show an association with upper aero-digestive tumours." (PMID 38396870, 2024).
kidney disease (3 papers, 2021 to 2025). "Taken together, these findings suggest that ALDH2 dysfunction not only has potential as a dual-purpose biomarker (diagnostic and prognostic) for kidney diseases but can also act as a promising therapeutic target to prevent and treat kidney diseases." (PMID 40968356, 2025). "Given our clinical data and animal experiments suggesting that altered ALDH2 activity and subsequent acrolein accumulation exacerbate kidney disease, we employed a cell culture model to uncover the underlying mechanisms." (PMID 39226171, 2024). "This study contributes to the field as it establishes a clear link between ALDH2 and kidney disease progression." (PMID 39226171, 2024). "To elucidate the causal relationship between diminished ALDH2 expression and the progression of kidney disease, we employed ALDH2 Glu504Lys–knockin mice in our animal experiments." (PMID 39226171, 2024). "While we utilized kidney gene expression data and urine analysis to demonstrate the negative correlation between ALDH2 expression and kidney disease progression, we were unable to obtain ALDH2 genotyping of the study individuals because of IRB restrictions." (PMID 39226171, 2024).
proliferative retinopathy (3 papers, 2015 to 2022). "One cross-sectional study (n = 212) demonstrated that proliferative retinopathy prevalence was significantly lower in ALDH2 *2 allele carriers than that in ALDH2 *1/*1 carriers (2.2% vs. 9.2% p<0.05)." (PMID 26599441, 2015). "And we first demonstrated that the slighter retinal disorders in T2DM would be related to the activation of the ALDH2/SIRT1 pathway." (PMID 34725563, 2021). "In contrast, a retrospective study (n = 234) revealed that, among drinkers, ALDH2 *2 carriers had a higher incidence of retinopathy than that in ALDH2 *1/*1 carriers." (PMID 26599441, 2015).
bacterial infection (2 papers, 2021 to 2025). "The purpose of this study is to understand the roles of ALDH2, and the effects of ALDH2*2 mutation, alcohol drinking, and bacterial infection on dental bone loss." (PMID 33925003, 2021). "Notably, a recent preprint study reported that ALDH2 negatively impacts host defense against bacterial infection, raising the possibility that cGAS loss‐induced ALDH2 activation may enhance host protection against bacterial infection." (PMID 41042077, 2025).
inflammation (2 papers, 2021 to 2023). Aberrant reaction of the microcirculation characterized by movement of fluid and leukocytes from the blood into extravascular tissues. "Genetic ALDH2-deficient mice are prone to ethanol-induced liver inflammation and fibrosis by paracrine activation of IL-6 in Kupffer cells." (PMID 34764958, 2021). "ALDH2-deficient mice are susceptible to alcohol-induced liver inflammation." (PMID 37891964, 2023).
neurological disorders (2 papers, 2022 to 2025). "The availability of lipid profiles will provide more insights into the role of ALDH2 in brain injury, thus opening up opportunities for drug development and treatment of alcohol-induced neurological disorders." (PMID 36743287, 2022).
brain disease (1 paper, 2017). "Previous studies have demonstrated that miRNAs control diverse aspects of brain disease, including cerebral I/R injury, and that miRNAs are involved in regulation of ALDH2 expression." (PMID 29245933, 2017).
hematological disorders (1 paper, 2024). "In a total of 417 samples with IBMFS or associated hematological disorders, targeted proteomic analysis was found to provide a simple and direct diagnostic contribution for both patients with SDS and ADH5/ALDH2 deficiency." (PMID 38740980, 2024).
respiratory system diseases (1 paper, 2025). "In summary, these results demonstrate that ALDH2 plays a distinct and specific role in respiratory system diseases." (PMID 40968356, 2025). "Emerging evidence has demonstrated that ALDH2 plays a broad role in regulating cell death sensitivity and autophagy to delay the development of respiratory system diseases." (PMID 40968356, 2025). "A deeper understanding of the regulatory mechanisms of ALDH2 could lead to improved strategies for preventing and treating respiratory system diseases." (PMID 40968356, 2025).
ALDH2 also shares sentences with these, for which no sentence is quoted: essential hypertension (8 papers); stomach cancers (7); acute myocardial infarction (5); Glucose intolerance (5); aortic aneurysm (3); laryngeal carcinoma (3); Myelodysplasia (3); acute leukemia (2); adenocarcinoma (2); alcohol-related disorders (2); alcoholic cardiomyopathy (2); anxiety disorder (2); atrophic gastritis (2); autoimmune disease (2); breast tumor (2); dilated cardiomyopathy (2); dwarfism (2); Hyperammonemia (2); hyperlipidaemia (2); hyperprolinemia type 2 (2); inherited bone marrow failure syndrome (2); intracerebral hemorrhage (2); malaria (2); pancreatitis (2); parasite infection (2); upper tract urothelial carcinoma (2); Abdominal obesity (1); age-related macular degeneration (1); amyloid (1); aneurysm (1).
A further 87 diseases each share a sentence with ALDH2 in 1 paper.